AKT1 (AKT serine/threonine kinase 1)
Diseases named in the same sentence as AKT1 in open-access papers (continued):
Sharing a sentence is not in itself a finding about the gene and the disease.
tumor (continued). "Capivasertib (AZD5363, Truqap) competitively interacts with the ATP binding site of all three AKT isoforms (AKT1/2/3) and inhibits AKT’s catalytic activity with high potency and higher selectivity than previously developed compounds, resulting in the arrest of tumor cell growth." (PMID 38954770, 2024). "While we observed an enrichment of such pathway in our recurring primary tumor set, there was no significant increased frequency in PIK3CA or AKT1 mutations when compared to frequencies reported in the TCGA sample set (PIK3CA p = 0.060; AKT1 no mutations detected)." (PMID 36732562, 2023). "This process is caused by the overexpression of HIF1-α, mediated by the mTOR pathway through the alteration of tumor suppressor genes, such as serine/threonine kinase 11 STK (STK11), TSC complex subunit 1 (TSC1), TSC complex subunit 2 (TSC2) and AKT serine/threonine kinase 1 (AKT1)." (PMID 37239099, 2023). "Moreover, the trend relationship analysis revealed that the relative expressions of AKT1 were upregulated in HCC tumour tissues compared with the normal samples." (PMID 35811356, 2022). "Also, the tumor phospho‐Akt1/2/3 levels are not significantly different between different KRAS mutation status (one‐way ANOVA, P > 0.05)." (PMID 34919787, 2022). "On the other hand, for phagocytosis experiment, both silencing AKT1 and AKT2 reduced phagocytosis of dying cells, and silencing of both AKT1 and AKT2 reduced the expression of LC3‐II, which indicated that both AKT1 and AKT2 played roles in engulfment of dying tumor cells by macrophages." (PMID 35037422, 2022). "Conversely, mutations in AKT1 and ESR1 did not prevent tumor response." (PMID 35565291, 2022). "We found that the injection of 5-HT could significantly promote tumor growth, but there was no significant increase in growth with 5-HT treatment in the Akt1 knockout groups." (PMID 35664068, 2022). "In any case, the data that we present here suggest that Palbociclib in combination with inhibitors of factors including AKT1, STING, or IKK may provide an eventual strategy to modulate the SASP-related, inflammatory environment that could augment anti-tumor responses in a context-dependent manner." (PMID 35158840, 2022). "Unlike AKT2 and AKT3, dysregulation or activation of AKT1 is essential for tumor development." (PMID 33568640, 2021). "Mammary gland-specific cell-autonomous Akt1 deletion inhibited tumor growth but not metastasis." (PMID 34298660, 2021). "Our data demonstrated for the first time that α2β1 is involved in the protection of tumor cells against senescence and that senescence, which is induced by the downregulation of α2β, is based on a signaling mechanism in which Akt1 performs a non-canonical function." (PMID 34257160, 2021). "In agreement with the mixed normal and tumor datasets, PBMC displayed positive correlations between ACE2/TMPRSS2, TMPRSS2/FURIN, ACE2/TFRC, FURIN/TFRC, TMPRSS2/CTSL, FURIN/CTSL, TMPRSS2/MYC, and FURIN/AKT1 and a negative association between ACE2/ADAM17." (PMID 33796097, 2021). "However, by Sanger sequencing, we did not detect mutations at the established hotspots in AKT1, SMO, KLF4 and TRAF7, suggesting different tumor drivers acting in this age group." (PMID 34495383, 2021). "CircPLEKHM3 was found to function as a tumor suppressor in OC by sponging miR-9 to regulate the endogenous expression of breast cancer 1 (BRCA1), DNA heat shock protein family (Hsp40) member B6 (DNAJB6) and kruppel like factor 4 (KLF4) which consequently inactivates oncogenic AKT1 signaling." (PMID 33614648, 2021). "Furthermore, within the mTOR signalling pathway, we found several oncogenes, including mTOR, AKT1 and AKT2 and tumour suppressor genes that were significantly upregulated for subtype-1 tumours and all of which have previously been linked to pancreatic carcinogenesis." (PMID 34506537, 2021).
tumor (continued). "In addition, Akt1-related pathways could affect the expression of EMT markers such as Snail1, E-cadherin, and N-cadherin, which promote tumor metastasis." (PMID 33911067, 2021). "NF-κB RelA/p65 promotes lung epithelial cell tumour growth in vivo by downregulating the metastasis suppressor CD82 and enhancing the epithelial-to-mesenchymal cell transition via integrin-mediated signalling involving the mitogenic ERK, Akt1 and Rac1 proteins." (PMID 34503110, 2021). "Interestingly, no changes in the phosphorylation of the IGF1-dependent signal transducer AKT (also known as Akt1), as well as of ERK1/2 (Mapk3/Mapk1) and p38 (Ahsa1) were observed in the skeletal muscle of tumor-bearing animals relative to the respective controls." (PMID 31915140, 2020). "In colorectal cancer cells, phosphorylation by Akt1/2 on Smurf1 Thr145 augments Smurf1 protein stability to control DAB2IP abundance, which contributes to increased ubiquitination and degradation of tumor suppressor DAB2IP, dampening DAB2IP’s inhibitory effect on tumor cells." (PMID 33718111, 2020). "In addition, VEGF‐induced corneal angiogenesis and tumor development were significantly inhibited in mice lacking Akt1." (PMID 30984553, 2019). "Tumor volumes and vessel area were significantly reduced in mice lacking Akt1." (PMID 30984553, 2019). "We identified seven oncogenes (NRAS, EGFR, RXRA, HRAS, KRAS, AKT1, ERBB2; q<0.10) and seven putative tumor suppressor genes (ARID1A, TXNIP, CTNNB1, PIK3RI, CDKN2A, KLF5, STAG2; q<0.10) significantly regulated between tumor and control, which were formerly reported to be altered in BC." (PMID 30419021, 2018). "Furthermore, 16% of AKT1-mutant tumours display no additional alterations involved in disease progression suggesting that AKT1E17K is a potent oncogenic driver." (PMID 28082369, 2017). "Similarly, knockdown of Akt1 and Akt3 significantly hampered cell proliferation in vitro and tumor growth in vivo, but Akt2 knockdown did not." (PMID 29090098, 2017). "Similarly, in T47D xenografts AKT1 silencing reduced tumor growth, whereas AKT2 silencing did not change the growth rate compared to control tumors." (PMID 28287129, 2017). "Furthermore, the three AGC kinases AKT-1, AKT-2, and SGK-1 that in most previous studies have displayed redundant activities as negative regulators of DAF-16, have antagonistic roles in DAF-16 mediated tumor formation." (PMID 28549065, 2017). "Although Myr-AKT1 transgenic mice show decreased RTK expression, this hyperactive allele is sufficient to propagate downstream signaling to enhance phenotypes that control tumor progression, even in the presence of the negative feedback." (PMID 27004402, 2016). "Results from our ChIP-Seq analysis identified oncogenic c-Myc, Cyclin D1, Ets2, Akt1 and Notch2, pro-inflammatory Hsp90, pro-lymphangiogenic VEGF-C, and pro-apoptotic p27 as novel transcriptional targets of MTA1, revealing its ability to simultaneously activate multiple tumor-promoting pathways." (PMID 26943043, 2016). "Of course, since our analysis was performed on the entire tumor tissue, the possibility that AKT1 and PIK3CA mutations existed in different cells within the tumor could not be excluded." (PMID 27515171, 2016). "A recent study indicates that in PTEN-deficient tumours, AKT2 is the active isoform but not AKT1." (PMID 26528548, 2015). "For example, if genomic information from the primary tumour was used to inform therapeutic decision-making for patients 63 and 160, the AKT1 and ERBB2 amplifications would not have been evident and these patients would not have been considered for HER2 or AKT-mTOR pathway directed therapies." (PMID 25886454, 2015). "In addition, overexpression of SKP2 did not modify the ratio of tumor types developed in SKP2/myr-AKT1 mice when compared with myr-AKT1 mice." (PMID 25537506, 2015).
tumor (continued). "Therefore, we might hypothesize that the different AKT1 genotypes might affect its inhibition by PTEN after stimulation by miR-21, favouring tumor-induced muscle wasting through apoptosis induction." (PMID 25238546, 2014). "We also found that receptor mediated-[Ca2+]i increase and phosphorylation of akt1/PKB consequent to PI3K activation are impaired in NK cells upon treatment with fluvastatin; this could explain the inhibition of lysis of different tumor targets in a short-time cytolytic assay." (PMID 23667543, 2013). "Furthermore, co-transfection of BRG1 siRNA and p-Akt1 restored cell growth accompanied by upregulation of p-Akt, p-GSK-3β and cyclin D1 levels, whereas transduction of PTEN siRNA decreased tumour-suppressing effect of BRG1 silencing." (PMID 21102582, 2011). "In each case, mutant Akt1 delayed involution but did not induce tumor formation." (PMID 21646685, 2011). "Finally, the gene-set #2 also contained several tumour suppressors (EPHA3 and EPHB2) and proto-oncogenes (AKT1, AURKA, ETV6, MITF and PIK3CA), which expands on the observed enrichment of the immune response and suggests that this gene-set has a critical role in breast tumorigenesis." (PMID 19826428, 2009). "Furthermore there was no sign of tissue distortion or tumor formation in brain of ICH animals grafted with F3 or F3.Akt1 hNSCs 6 months PT." (PMID 19440551, 2009). "Expression of activated Akt1 in MMTV-c-ErbB2 mice accelerates tumourigenesis with a reduced requirement for signalling through the EGFR family, as well as a reduced requirement for a subset of downstream signaling molecules with a metabolic shift in the tumours from bitransgenic mice." (PMID 18700973, 2008). "Therefore, the performed molecular docking experiments were designed to identify drugs that could inhibit the tumor-inducing overexpression of Akt1 and Akt2 without simultaneous inhibition of MAO-B." (PMID 39714760, 2025). "Thus, through phosphorylation of ME2fl, AKT1 enhances the glycolytic capacity of tumor cells in vitro and in vivo, revealing an unexpected role for subcellular translocation switching of ME2 mediated by AKT1 in the metabolic adaptation of tumor cells to growth stimuli." (PMID 38263319, 2024). "We hypothesize that potential compensation by AKT1 might explain why the CRIPSR KO AKT2 cells did not recapitulate the decreased subcutaneous tumor growth or the full prophylactic protection observed for the shRNA AKT2 KD cells, although we have not explicitly tested this hypothesis." (PMID 37894325, 2023). "The differential features in the HCC clones with the same AKT1/NRAS integration sites may be due to the intratumoral differentiation and in vitro selection of the HCC clones originated from the same transformed hepatocyte which gained growth advantage in the very beginning of tumor progression." (PMID 35721518, 2022). "Despite the attenuation of several signalling events in the bitransgenic tumours when compared with the c-ErbB2 tumours both tumour types maintain similar levels of phosphorylated/activated Erk indicating that transgenic activation of Akt1 does not bypass Erk signalling." (PMID 18700973, 2008). "Gene expression analysis in tumor tissues revealed that ACN, whether used alone or in combination with DOX, significantly downregulated several key genes associated with BC metastasis, such as HIF, Cd44, Rgcc32, CREB, PI3K/Akt-1, which were not effectively suppressed by DOX alone." (PMID 40806360, 2025).
tumor (continued). "Results were presented for the ITT population and for a subgroup of patients with genetic alterations in tumor tissue of PIK3CA, PTEN, and AKT1 (the latter will not be presented here)." (PMID 39742383, 2024). "In detail, PTEN loss was determined via IHC using the absence of PTEN staining in 50% or more of the specimen’s tumor area; NGS to examine PTEN status or PIK3CA/AKT1/PTEN alteration was performed using a FoundationOne CDx NGS assay." (PMID 37894312, 2023). "Although highly homologous, the AKT isoforms exert, indeed, distinct, non-redundant effects in BC, with AKT1 displaying a tumor-initiating role and AKT2 being mainly involved in tumor progression and metastasis." (PMID 35628294, 2022). "The formation of poorly differentiated BCs was convincingly observed in syngeneic mice tumor grafts with either PDK1- or PKCα-expressing cells, but not AKT1-expressing cells." (PMID 35159078, 2022). "The results showed that the expression levels of AKT1 in OSCC tissues were not significantly correlated with age, sex, tumor stage, tumor size, lymph nodes, tumor differentiation, or smoking and alcohol consumption history." (PMID 35756492, 2022). "High expression levels of AKT1 (p = 0.01), IFNGR1 (p = 0.01), and BRCA2 (p = 0.02) were predictive of early trabectedin treatment failure, irrespective of tumor grade." (PMID 35267598, 2022). "Strikingly, the simultaneous injection of myr-AKT1, TAZS89A, and dnRBP-J did not hamper tumor development in mice, which required to be sacrificed by 13 weeks post-injection due to high tumor burden." (PMID 35655220, 2022). "It has been reported that AKT1 does not promote invasive phenotype, while AKT3 is required for TNBC proliferation and tumor growth." (PMID 34199634, 2021). "Overall, the results indicate that motif 3 (UCA1/AKT1/hsa-miR-125b-1) has the best predictive power in distinguishing metastatic and non-metastatic phenotypes of SKCM tumor samples." (PMID 32703153, 2020). "Under some conditions, AKT2 is suggested to have an inhibitory effect on proliferation and tumor growth, however the role of AKT2 in cell cycle regulation and apoptosis is not as clear as the function of AKT1." (PMID 31752925, 2019). "The low expression level of AKT1 in ER negative and HER2 negative tumor is consistent with low expression in basal-like tumor which is ER and HER2 negative." (PMID 28301567, 2017). "In addition to AKT1 and its substrates, we found a densely connected group of kinases that regulate the mitotic cell cycle in the SMAD4 dependency network, suggesting that SMAD4 mutant tumor cell lines may have an increased sensitivity to perturbation of this process." (PMID 26947069, 2016). "In our cells, siRNA inhibition of AKT1/2 was partial and resulted in increased tumor cell survival, while suppression of AKT3 had no impact on tumor cell survival in the clonogenic assay." (PMID 22480225, 2012). "The expression analysis showed that ESR1 had no expression difference between normal and tumor groups; BCL2 expression was lower in tumor group (P < 0.001); while AKT1, CCND1, and HIF1A expressions were higher in tumor group compared with those in normal group (all P < 0.001)." (PMID 40552073, 2025). "However, some mice receiving Akt1-OE CTLs displayed extremely elevated ALT levels on day 10, despite no decrease in tumor burden." (PMID 40139836, 2025). "However, we previously reported that phospho-ERK1/2 or phospho-Akt1/2/3 were not upregulated in CRC tumor compared to matched mucosa tissues, and in fact in most cases, downregulated in tumor." (PMID 37051535, 2023). "Referring to the TCGA HNSC tumor dataset, we found a positive correlation between IFN-γ-related genes (IFN-γ, CD8A, and STAT1) and PD-L1 (CD274), but not between EGF-related genes (EGFR, AKT1, and MAP2K7), which seems to support the results of this study." (PMID 35456895, 2022).
tumor (continued). "Furthermore, expanded genetic testing identified PIK3CA, AKT1, and PTEN alterations in 25% of the tumours originally classified as pathway non-altered." (PMID 35671774, 2022). "The tumor suppresser, 12-O-Tetradecanoyl phorbol-13-acetate (TPA)-inducible sequences 21 (TIS21), an ortholog of B-cell translocation gene 2 (BTG2), inhibited TNBC cell growth and invasion via activation of Akt1 and not Akt2." (PMID 34298660, 2021). "In this experiment, treatment with the Akt2 or Akt1/2 inhibitor plus DEX shows a significant anti-leukemic effect with reduced tumor size and prolonged overall survival of mice when compared with DEX alone, while treatment with the Akt1 inhibitor plus DEX did not achieve these results." (PMID 30598523, 2019). "Strikingly, although Akt1 was not significantly different between the selected cohorts, a trend towards increased TGFβ1, CDH2 (N-cadherin) and Snail were observed in the metastatic tumor sites (N=114) compared to the tumors localized in the prostate (N=4)." (PMID 31360736, 2019). "Amplification of relevant genes, including AKT1, Kirsten rat sarcoma (KRAS), and proto-oncogene tyrosine-protein kinase Yes (YES1), were detected (data not shown) but were not enriched in the osimertinib-resistant xenograft tumor, osimertinib-3." (PMID 29764505, 2018). "Noticeably, the tumor suppressor proteins whose levels have been shown to be downregulated by SKP2-dependent degradation in various tumor types, including p27, p57, Dusp1, and Rassf1A were not decreased in liver lesions from SKP2/N-RasV12 and SKP2/myr-AKT1 mice." (PMID 25537506, 2015). "However, while Akt1 is required for efficient tumour formation in MMTV-ErbB2 mouse models, activation of Akt1 alone is not sufficient for mammary tumourigenesis indicating that other pathways downstream of ErbB2 activation are important for tumour formation." (PMID 18700973, 2008). "Moreover, in contrast to previous reports in HBC73–75, PIK3CA and other PI3Ks activating AKT as well as AKT1 and AKT3 were downregulated or not differentially expressed in tumours, suggesting that subtypes evaluated here are not likely to respond to therapies targeting PI3Ks and AKT inhibitors." (PMID 36220861, 2022). "As the PI3K-AKT signaling pathway plays an important role in the regulation of tumor progression 26, 27, we then analyzed the relationship between CCDC65 and PI3K-AKT signaling pathway and found that CCDC65 significantly suppressed the levels of p-AKT1 (Ser473), but not total AKT1 protein." (PMID 34335983, 2021).